CP (ceruloplasmin)
Diseases named in the same sentence as CP in open-access papers (continued):
Sharing a sentence is not in itself a finding about the gene and the disease.
breast cancer (continued). "Our data provide insight into the mechanism of CP against breast cancer progression and would benefit the medical practitioners in better management with CP usage." (PMID 34122605, 2021). "Ceruloplasmin expression was also associated with the infiltration levels of CD4+ T cells, neutrophils, and dendritic cells in basal-like breast cancer." (PMID 34413268, 2021). "Ceruloplasmin expression was remarkably associated with the infiltration abundances of CD8+ T cells, neutrophils, and dendritic cells in luminal B breast cancer." (PMID 34413268, 2021). "In this paper, we explore the action of water extract of CP on 4 different types of genomic compositions of breast cancer cells (for details)." (PMID 34122605, 2021). "The study intended mainly to explore and compare the mechanisms by which CP exhibit its antiproliferative and antimetastatic potential on different breast cancer cells that vary by their genomic profile." (PMID 34122605, 2021). "Changes in the paramagnetic centers can serve as a biomarker of breast cancer development because they reflect functional changes of ceruloplasmin and transferrin." (PMID 28849262, 2017). "Ceruloplasmin and transferrin are proteins which play a potential role in the process of breast cancer development." (PMID 28849262, 2017). "As compared to the control subjects, lipid peroxidation and GPx1 activity were significantly higher in the breast cancer cases, whereas ceruloplasmin activity was decreased." (PMID 26446998, 2015). "Altered serum ceruloplasmin levels after treatment (chemotherapy or radiation) have been observed in many patients with malignancies, such as laryngeal, cervical and breast cancers." (PMID 23251472, 2012). "In the 1980s however, the acute phase proteins alpha-2-macroglobulin and ceruloplasmin were already studied in relation to breast cancer, using immunoassay methods." (PMID 21871081, 2011). "In the study of breast cancer, it was discovered that the level of ceruloplasmin expression was closely connected to immune cell infiltration, and M2 macrophages were negatively correlated with ceruloplasmin." (PMID 36814682, 2023). "Invasive breast cancer and ICT infiltration have been associated with low expression of CP." (PMID 37284310, 2023). "Higher CP expression is related to shorter overall survival (OS) of patients with breast cancer." (PMID 36237302, 2022). "Interestingly, a recent study showed reduced CP in whole blood of patients with breast cancer after delivery of radiation." (PMID 35918659, 2022). "In contrast, ceruloplasmin (CP) expression is downregulated in breast cancer." (PMID 36237302, 2022). "MDA-MB-231 cell migration was observed for 24 h and it was observed that the wound area increased in the cells, which were treated with Cur, CP, Au-C, and Au-CP, indicating that they could inhibit the motility of breast cancer cells." (PMID 35216264, 2022). "Decreased cellular migration in the wound areas which were treated with Cur, CP, Au-C, and Au-CP was observed, indicating that they could inhibit the mobility of breast cancer cells." (PMID 35216264, 2022). "Based on the different subtypes of BRCA, we observed that ceruloplasmin expression was significantly associated with the infiltration abundances of CD4+ T cells, CD8+ T cells, neutrophils, macrophages, and dendritic cells in luminal A breast cancer." (PMID 34413268, 2021). "In this paper, we study the direct effect of CP and its conditioned medium on four different mutant types of breast cancer cells, wishing to pinpoint the molecular mechanism that could be affected." (PMID 34122605, 2021). "In breast cancer, elevated ceruloplasmin has been found in patients with metastatic disease." (PMID 28423673, 2017). "In breast cancer lung metastases, stromal POSTN is crucial for cancer stem cell maintenance by increasing Wnt signaling 36, and LTBP2+/POSTN+ CP-CAFs constitute the majority of ECM-CAFs." (PMID 36438498, 2022).
breast cancer (continued). "The CP extract consists a group of single compounds and so it was not surprising that breast cancer cells with different genomic compositions would react very differently upon CP treatment." (PMID 34122605, 2021). "CP is rarely expected to be negative in the diagnosis of malignant mammary tumors, thus in such cases therapeutic procedures and further prognosis would be more precise." (PMID 29360854, 2018).
Alzheimer disease (26 papers, 2013 to 2025). A progressive, neurodegenerative disease characterized by loss of function and death of nerve cells in several areas of the brain leading to loss of cognitive function such as memory and language. "Here, we report that the Alzheimer’s disease risk factor CALM controls the surface levels of CP-AMPARs and thereby reciprocally regulates LTP and LTD in vivo to modulate learning." (PMID 35613266, 2022). "Ceruloplasmin loss-of-function is involved in neurodegenerative syndrome, whereas high ceruloplasmin level is associated with copper toxicity, Alzheimer’s disease and cardiovascular diseases." (PMID 32620920, 2020). "CP-Tg mice were crossed to APdE9 mice, a model of Alzheimer’s disease that develops prominent Aβ pathology and develops spatial memory impairments by 12 months of age." (PMID 35197825, 2022). "Future studies should, therefore, not only study the CP expression profile in diseases such as Alzheimer’s disease (AD), but also the overall CP response to inflammatory stimulus elicited both in the circumventricular space and within the brain parenchyma." (PMID 26236190, 2015). "The expression of the transcript for ceruloplasmin was upregulated in the olfactory bulb across all stages of Alzheimer’s disease as well as being increased at the protein level in the CNS of patients with Alzheimer’s disease." (PMID 38667304, 2024). "There are also deficits in ceruloplasmin in Alzheimer’s disease." (PMID 23536801, 2013). "Briefly considering common disease themes between Alzheimer’s disease and the ALS-Ox subtype, expression of oxidation-associated transcripts COX4I2, NDUFA4L2, and OXR1 is consistent with reported literature, although CP is known to be upregulated in Alzheimer’s55." (PMID 36609402, 2023). "However, the role of CP in Alzheimer’s disease (AD) is unclear." (PMID 37362028, 2022). "A subset of patients with Alzheimer’s disease (AD) or its prodromal form, known as Mild Cognitive Impairment (MCI), fail to maintain a normal copper metabolic balance and exhibit higher than normal values of non-ceruloplasmin copper." (PMID 32784855, 2020). "Although the copper:zinc ratio is not as high as for most patients with type 3 Alzheimer's disease, the free copper (estimated by serum copper minus three times ceruloplasmin) is high." (PMID 26870879, 2016).
diabetes (26 papers, 2007 to 2025). "CP is an acute phase protein that is activated under a variety of circumstances, including inflammation, infection, diabetes, and trauma." (PMID 37637428, 2023). "Serum CP levels are significantly raised in patients with diabetes that exacerbates the progression of DCM to heart failure." (PMID 36238639, 2022). "The results mostly confirmed the interaction in CP abundance by showing a decrease after surgery in the diabetes remission group and an increase in the persistent diabetes group." (PMID 34501327, 2021). "Trace elements related-metalloproteins, such as ceruloplasmin, and lipid metabolism and transport-related apolipoprotein C are important in the progression of diabetes and are expected to be candidate plasma biomarkers of T2DM." (PMID 32817751, 2020). "With respect to establishing its efficacy in treating diabetes, it is necessary to investigate the pharmacokinetic behavior of multiple active compounds in the extract of CP leaves." (PMID 31406501, 2019). "The aim of this prospective study is to investigate the relationship between plasma levels of five acute-phase proteins (CRP, ceruloplasmin, alpha-1-antitrypsin, orosomucoid, and haptoglobin) at baseline and incidence of diabetes in a population-based cohort." (PMID 27581604, 2016). "This is so because studies have shown that measurement of serum CP provides an accurate assessment of residual beta-cell function and thus has been widely used as a marker of insulin secretion in patients with diabetes." (PMID 25945127, 2014). "Our previous investigation of the reactive phenotype of Müller cell in rats with 6 months of diabetes identified the upregulation/induction of α2-macroglobulin, ceruloplasmin, and other acute-phase proteins as a major component of Müller cells reactivity." (PMID 22615852, 2012). "Liver and kidney MT and plasma CP levels were elevated in diabetic rats, suggesting that there may be elevated intracellular copper levels in the liver and kidney in diabetes mellitus." (PMID 36238639, 2022). "After performing the dimension reduction from the 24 overlapping DEPs from discovery and validation datasets, a 4-protein classifier (SERPINA5, VPS4A, CP, TF) could distinguish diabetes from DKD3." (PMID 34963468, 2021). "Increased ceruloplasmin levels seen in diabetes mellitus may be a protective response to an increase in circulating unbound Fe2+, which would act as a catalyst for further free radical-induced lipoperoxidation." (PMID 33680612, 2021). "CP leaves have long been used as a traditional Chinese medicinal herb, as they have heat- and toxin-clearing attributes and are used to treat obesity and diabetes; the leaves have also been historically consumed as nutraceutical tea." (PMID 31406501, 2019). "Ceruloplasmin and alpha-1-antitrypsin were less markedly raised in participants with diabetes." (PMID 27581604, 2016). "High dose vitamin C, used in EDTA chelation therapy, has been shown to have a pro-oxidant effect and ceruloplasmin, a copper containing metalloenzyme, has been suggested to have a pro-oxidant effect in conditions of increased oxidative stress, such as diabetes, by the disruption of copper binding." (PMID 17316429, 2007). "It should be noted that the concentrations of acute-phase proteins—including ceruloplasmin (CP), transferrin, and albumin—may not reliably indicate iron metabolism in the context of diabetes-associated chronic inflammation and oxidative stress." (PMID 40871742, 2025). "Moreover, the abundance of CP (spot 650) only increased in the diabetes remission group." (PMID 34501327, 2021). "The results are in accordance with a study from the Malmö Preventive Project, which reported nonsignificant relationships for ceruloplasmin, alpha-1-antitrypsin, haptoglobin and orosomucoid and incident diabetes after adjustments for fasting glucose and other risk factors." (PMID 27581604, 2016).
diabetes (continued). "The time course of GFAP, α2-macroglobulin, and ceruloplasmin overexpression in the retina of diabetic rats was similar to that of IL-1β with no changes as compared to control rats at 1.5 months from the induction of diabetes and a significant upregulation after 3 months of diabetes." (PMID 22615852, 2012). "Moreover, a 4-protein (SERPINA5, VPS4A, CP, TF) classifier was built to predict early stage DKD3 from diabetes." (PMID 34963468, 2021). "CP levels were elevated in patients with acute MI and Diabetes Mellitus (DM) compared to non-diabetics with MI, possibly because of the greater degree of inflammation in these patients." (PMID 33096845, 2020). "The correlation between the CP levels and the extent of heart failure was independent of gender, smoking, alcohol taking, hypertension, diabetes mellitus, AST, uric acid, CKMB, CRP, LVEF, and other parameters." (PMID 23781119, 2013). "Notably, iron accumulates in the brains and livers of patients with absent/dysfunctional ceruloplasmin and ceruloplasmin knockout mice, which in turn leads to diabetes and dementia." (PMID 30147446, 2018). "Regarding differences among the non-diabetic, diabetes remission, and persistent diabetes groups, considering the samples obtained before and after surgery as a whole, we found different abundances in nine spots from five proteins: CP, SERPINA1, ITIH4, plasminogen (PLG), and FGG." (PMID 34501327, 2021). "Finally, since diabetes represents a factor that affects the levels of circulating TRAIL, we performed a further analysis of the correlation between TRAIL and ceruloplasmin in the subgroup of samples without diabetic subjects that confirmed the strength and independence of the association." (PMID 30147446, 2018).
Obesity (26 papers, 2014 to 2024). Accumulation of substantial excess body fat. "Adipokines, such as adiponectin and leptin, but also ceruloplasmin, have been linked to systemic inflammation, with adipogenesis contributing to the production of pro-inflammatory cytokines in obesity." (PMID 38256185, 2024). "Elevated serum ceruloplasmin levels have been linked to obesity due to increased pro-oxidant activity." (PMID 38923963, 2024). "Recent studies indicated that the expression level of ceruloplasmin, identified as an adipokine, is significantly increased in adipose tissues of obese individuals and obesity-associated cancer cells." (PMID 34413268, 2021). "In summary, we have through bioinformatic screening identified ceruloplasmin as a novel adipokine with increased expression in adipose tissue of obese subjects as well as in cells from obesity-associated cancers." (PMID 24676332, 2014). "In summary, by bioinformatically performing a systematic screening for genes overexpressed in obesity associated cancers, this study identified ceruloplasmin as a novel human adipokine." (PMID 24676332, 2014). "Nevertheless, we can state that CP is overexpressed in obese adipose tissue and in cancer cells associated with obesity." (PMID 24676332, 2014). "However, the major circulating Cu transporter, ceruloplasmin, is elevated in the serum of individuals with obesity and is associated with inflammation." (PMID 39796597, 2024). "Other obesity–cancer association mechanisms include obesity-induced chronic inflammation; increased aromatase expression, circulating levels of estrogen, insulin, leptin and ceruloplasmin; and decreased amounts of adiponectin and sex-hormone-binding globulin." (PMID 35741001, 2022). "High serum C3 and plasma CP enzyme levels have been associated with obesity." (PMID 33672392, 2021). "Similarly, an increase in heme protein hemopexin (HPX) and cuproprotein ceruloplasmin (CP) levels has been associated with increased triglyceride levels and obesity, respectively." (PMID 34066295, 2021). "Whether there is a causal relationship between adipose overexpression of ceruloplasmin and cancer development in obesity cannot be answered by these cross-sectional comparisons." (PMID 24676332, 2014). "We found expression of ceruloplasmin to be the most enriched in obesity-associated cancer cells." (PMID 24676332, 2014). "While these studies relate elevated serum copper to obesity and associated conditions, our data suggest consumption of sugar-sweetened beverages, especially glucose containing beverages, by healthy subjects, decreases serum copper and ceruloplasmin ferroxidase activity." (PMID 32854403, 2020). "In the same context, the protein ceruloplasmin has also been found to be up-regulated in EVs from fat depots under conditions of lipid hypertrophy and obesity, in particular, in visceral and brown adipose tissues." (PMID 36830957, 2023). "More investigation is needed as to the roles of ANGPTLs and the effects of ceruloplasmin on angiogenesis in human obesity-related tumours." (PMID 36038791, 2022). "Other differential proteins expressed in neutrophils from patients with obesity and non‐obesity were the fetuin A and ceruloplasmin." (PMID 35818731, 2022). "Serum ferritin and serum ceruloplasmin were most often used in Canada; assessment of associated conditions, e.g. T2DM, obesity, and impaired glucose tolerance, was most likely in the Middle East." (PMID 34977520, 2022). "Along with serum Cu concentration, the ceruloplasmin, as the body's main Cu carrier, is overexpressed in adipose tissue and obesity-related cancer cells." (PMID 35782923, 2022). "Given the link between CP-AMPARs and plasticity of silent synapses (see “Introduction”), we also determined the proportion of silent synapses in obesity-prone males following JF consumption." (PMID 32731252, 2021). "Obesity is accompanied by increased plasma ceruloplasmin levels and increased copper concentration in visceral fat." (PMID 32854403, 2020).